FOXA1 (forkhead box A1)
Diseases named in the same sentence as FOXA1 in open-access papers (continued):
Sharing a sentence is not in itself a finding about the gene and the disease.
osteosarcoma (14 papers, 2019 to 2025). A usually aggressive malignant bone-forming mesenchymal neoplasm, predominantly affecting adolescents and young adults. "For instance, lncRNA TUG1 was identified as an oncogene in osteosarcoma and enhanced osteosarcoma cell growth through modulating the expressions of miR‐212‐3p and FOXA1." (PMID 31984680, 2022). "For example, lncRNA TUG1 interacts with miR-212-3p to enhance cell proliferation and restrain apoptosis by regulating FOXA1 in osteosarcoma." (PMID 32432654, 2020). "For example, lncRNA TUG1 promotes cell proliferation and suppresses apoptosis in osteosarcoma by regulating the miR-212-3p/FOXA1 axis." (PMID 32302291, 2020). "Silencing of SBF2-AS1 impairs the growth, migration ability and invasiveness of human osteosarcoma cell through upregulating miRNA-30a and inhibiting the expression of Forkhead Box A1 (FOXA1)." (PMID 32976115, 2020). "Furthermore, NR2F1-AS1 knockdown was reported to suppress cell invasion, migration, and cell growth, while it induced cell apoptosis in osteosarcoma cells by miR-483-3p and FOXA1." (PMID 34335755, 2021). "TUG1 recruited microRNA-212-3p from FOXA1 (Forkhead box A1) to expedite osteosarcoma progression." (PMID 33053117, 2020). "In osteosarcoma, it promoted proliferation by targeting FOXA1 signal." (PMID 33187481, 2020). "Thus, NR2F1-AS1 plays an oncogenic role in OS through sponging miR-483-3p and thereby upregulating FOXA1, suggesting an additional target for osteosarcoma therapeutics." (PMID 31801112, 2019). "Research had shown that NR2F1-AS1 upregulated FOXA1 through the adsorption of miR-483-3p, thus increasing the malignant degree of osteosarcoma and suggested it might be a potential therapeutic target for osteosarcoma." (PMID 34128858, 2021). "In osteosarcoma, NR2F1-AS1 accelerates proliferation and apoptosis resistance through both the miR-485-5p/miR-218-5p/BIRC5 and miR-483-3p/FOXA1 axes." (PMID 40828427, 2025). "In osteosarcoma, NR2F1-AS1 enhances cell motility through miR-483-3p/FOXA1 and miR-485-5p/miR-218-5p/BIRC5 pathways, contributing to ECM degradation and metastasis." (PMID 40828427, 2025).
metastatic disease (13 papers, 2016 to 2025). "In contrast, FOXA1 Class 2 mutations are clonally detected only in the metastatic disease and comprise frameshift mutations in the C-terminal half of the protein." (PMID 40570057, 2025). "Tumors with FOXA1 mutations accompanied by higher Gleason scores, shorter biochemical relapse time, and faster metastatic disease progression." (PMID 35251954, 2022). "Among other recurrent alterations in PCa, FOXA1 mutations have been reported at a frequency of 8–9% in primary disease and 12–13% in metastatic disease." (PMID 35220606, 2022). "However, further research is needed to determine if FOXA1 Class 2 mutations emerge spontaneously during natural disease progression—such as in de novo metastatic tumors—or are instead induced by the selective pressure of androgen/AR blockade." (PMID 40570057, 2025). "This indicates that the class 2 FOXA1 variants may be “hidden” in adenocarcinoma cases and are generally the indicators of poor prognosis among patients with metastatic disease." (PMID 39745364, 2025). "However, when examining FOXA1 class 1 to 3 alterations based on the variant allele frequency, we noted that the median variant allele frequency of each class was greater in metastatic tumors." (PMID 39745364, 2025). "Amongst these was the FOXA1 locus, which has been reported to harbor coding point mutations in ∼3% of localized tumors, 3′ UTR indels in an estimated ∼9% of metastatic tumors, and frequent structural rearrangements (∼11 to ∼35%) across a spectrum of primary and advanced disease." (PMID 39945744, 2025). "The high frequency of mutations in the genes RB1, TSC1 and FOXA1 in the metastatic samples with few or no concordant cases also suggests these genes are similarly relevant to the biology of metastatic disease." (PMID 32811538, 2020). "Furthermore, FOXA1 levels were decreased exclusively for the patients who received endocrine therapy in the adjuvant setting, and were indicative for resistance to endocrine intervention in metastatic disease." (PMID 29972720, 2018). "Together, these results suggest that FOXA1 3′-UTR indel mutations are prevalent in both primary and metastatic disease but do not show enrichment consistent with selection in advanced disease." (PMID 30272002, 2018).
thyroid cancer (13 papers, 2012 to 2025). "LncRNA MALAT1 knockdown can inhibit tumor migration and invasion while increasing autophagy via miR-200a-3p/FOXA1 axis in thyroid cancer cells." (PMID 36880066, 2023). "FOXA1 can be found in several organs, including thyroid tissues; its gradual overexpression was reported in advanced stages of thyroid carcinomas." (PMID 35887090, 2022). "Distinct roles of Foxa1 and Foxa2 are also consistent with our findings in C cell-derived thyroid cancer, suggesting that part of the developmental program is recapitulated in a tumor context." (PMID 26395490, 2015). "For instance, miR-132 targets FoxA1 and acts as a tumor suppressor in thyroid cancer." (PMID 33537240, 2020). "Also, FOXA1 is over-expressed in aggressive thyroid cancers (ATC) and involved in cell cycle progression via down-regulation of p27Kip1 in an ATC cell line." (PMID 24512546, 2014). "This showed that both FOXA1 and FOXA2 transcripts were enriched in MTC compared with thyroid cancer of follicular cell origin." (PMID 26395490, 2015). "Forkhead box A1 (FOXA1) is a protein found in the thyroid and is overexpressed in thyroid cancer." (PMID 39926108, 2025). "FOXA1 is highly amplified in AML patient samples and amplified in thyroid cancer." (PMID 39000600, 2024). "High expression levels of FOXA1 and FOXA2 were also evident in a RET-mutant MTC cell line (TT) but not in established lines from other types of thyroid carcinoma." (PMID 26395490, 2015).
non-small cell lung carcinoma (11 papers, 2018 to 2024). A group of at least three distinct histological types of lung cancer, including non-small cell squamous cell carcinoma, adenocarcinoma, and large cell carcinoma. "Real-time PCR assays and Western blot analysis confirmed that FOXA1 expression is reduced in post-treatment (PT) samples compared to non-small cell lung cancer (NSCLC) tissues." (PMID 39440051, 2024). "In addition, FOXA1 transcription factor has been identified as a potential regulator of PLOD2 expression during the progression of non-small cell lung cancer." (PMID 33014843, 2020). "Previous studies confirmed that SNHG17 promoted cell proliferation and migration by regulating FOXA1, XF1 and BIK expression in non-small cell lung cancer." (PMID 32351538, 2020). "Even though it is notoriously hard to inhibit transcription factors, elucidation of the mechanisms of action of FOXA1 in TNBC may lead to the identification of druggable targets, as was recently shown in a subset of non-small cell lung cancer cell lines." (PMID 38999963, 2024).
nasopharyngeal carcinoma (10 papers, 2019 to 2025). A carcinoma arising from the nasopharyngeal epithelium. "We analyzed the mRNA expressions of lncRNA RGMB-AS1 and FOXA1 in nasopharyngeal carcinoma tissues and adjacent tissues of 30 patients with nasopharyngeal carcinoma who underwent radical NPC resection." (PMID 35184697, 2022). "By contrast, the levels of lncRNA RGMB-AS1 and FOXA1 in nasopharyngeal carcinoma cells were significantly lower than those in NP69 cells." (PMID 35184697, 2022). "The RT-qPCR results showed that the expression levels of lncRNA RGMB-AS1 and FOXA1 in nasopharyngeal carcinoma tissues were significantly lower than those in their paired paracancerous tissues." (PMID 35184697, 2022). "First, second ranked FOXA1 was shown to suppress expression of miRNAs that were responsible for malignant behaviors in nasopharyngeal carcinoma, a subtype of head and neck squamous cell carcinoma." (PMID 33778495, 2021). "Importantly, the expressions of lncRNA RGMB-AS1 and FOXA1 were all significantly increased in nasopharyngeal carcinoma xenograft mice with overexpression of lncRNA RGMB-AS1." (PMID 35184697, 2022). "In nasopharyngeal carcinomas (NPC), TGF-β1 functions can be modulated from metastasis enhancer to tumor suppressor functions by the transcription factor FOXA1, showcasing dual functions of EMT regulators as will be discussed for EGF, too." (PMID 34771518, 2021). "Until now, the relationship between FOXA1 and the nasopharyngeal carcinoma (NPC) has not yet been reported." (PMID 32685483, 2020).
pancreatic ductal adenocarcinoma (10 papers, 2011 to 2024). An infiltrating adenocarcinoma that arises from the epithelial cells of the pancreas. "In PDAC, FoxA1 can promote metastasis, despite the fact low levels of FoxA1/2 (as well as other lineage specifiers associated with endodermal differentiation) are found in the subtype of pancreatic ductal adenocarcinoma that confers the worst prognosis." (PMID 30475207, 2018). "FoxA1 and FoxA2 were found to be expressed in most stages of pancreatic ductal adenocarcinoma progression." (PMID 39103560, 2024). "It reported that FOXA1 TF drives enhancer reprogramming during pancreatic ductal adenocarcinoma, thereby triggering an aberrant developmental transition toward embryonic endoderm." (PMID 31709755, 2020). "Recently, FOXA binding sites were identified in the E-cadherin promoter, and diminished FOXA1 expression was shown to result in decreased E-cadherin expression in poorly differentiated pancreatic ductal adenocarcinoma." (PMID 22590586, 2012). "In addition, FoxA1 inhibited the epithelial-to-mesenchymal transition (EMT) in pancreatic ductal adenocarcinoma." (PMID 32151057, 2020). "Meantime, a previous study also proved that miR-1290 could promote pancreatic ductal adenocarcinoma malignant progression by silencing the FOXA1/2, which was involved in epithelial-to-mesenchymal transitions." (PMID 32047539, 2020). "In addition, FOXA1 acts as an important antagonist of the epithelial-to-mesenchymal transition (EMT) in pancreatic ductal adenocarcinoma through its positive regulation of E-cadherin and maintenance of the epithelial phenotype." (PMID 24512546, 2014). "In contrast, FOXA1 and FOXA2 are positive regulators of E-cadherin, which suppress the EMT in pancreatic ductal adenocarcinoma." (PMID 21687740, 2011).
Breast Invasive Carcinoma (9 papers, 2018 to 2025). "The second objective of this study was to assess the relationships between AR, FOXA1, and the other clinical and pathological features of feline invasive mammary carcinomas." (PMID 31888566, 2019). "In the Breast Invasive Carcinoma (TCGA, Firehose Legacy) dataset, the TNBC subgroup comprised n = 69 samples, among which only 1 case exhibited a FOXA1 mutation (with no available mRNA expression data for NIS/SLC5A5), while the remaining samples were FOXA1 wild-type." (PMID 41283251, 2025). "We have checked the mRNA level of these genes in TCGA breast invasive carcinoma and found that FOXA1, PTGR1 and MTHFR showed an obvious negative correlation with miR‐522 level." (PMID 33369228, 2021).
lymph node metastasis (9 papers, 2012 to 2025). "FOXA1 mutations were found in 3/8 (38%) lymph node metastases and in 1/23 (4%) CRPC metastases, whereas SPOP mutations were detected in 1/8 (13%) lymph node metastases and in 2/23 (9%) CRPC metastases." (PMID 29988112, 2018). "Lower FOXA1 expression was primarily linked to UDC and advanced stages, marked by higher T stage (tumor sizes, T3-T4), N stage (lymph node metastasis, N2-N3), M stage (distant metastasis, M1) and clinical stage (III-IV)." (PMID 40623983, 2025). "FOXA1 protein was decreased in NPC cells; loss of FOXA1 associated with lymph node metastasis and poor prognosis." (PMID 33344262, 2020). "In addition to the GATA3/FOXA1 combination expression, tumor grade, pT stage, lympho-vascular involvement, lymph node metastasis, and extensive necrosis all contributed to DFS and CSS in the univariate analysis." (PMID 38425344, 2024). "FOXA1 is obviously related to lymph node metastasis (N classification; N0–N1 vs. N2–N3; P = 0.042)." (PMID 34503528, 2021). "In contrast, patients without lymph node metastasis were found to have more frequent mutation in four genes including GATA3, FOXA1, ANKRD11, and RET (P<0.05) and more CN amplifications in two genes including PIK3C2G and CCND2 (P<0.05)." (PMID 33968723, 2021). "Our finding that FOXA1 expression was lost only in a minority of lymph node metastases was surprising, as we expected the majority of lymph node metastases to exhibit negative FOXA1 staining." (PMID 22590586, 2012). "Still, our analysis shows approximately one quarter of lymph node metastases are negative for FOXA1." (PMID 22590586, 2012). "Five cases of lymph node metastases (23%) were negative for FOXA1 expression." (PMID 22590586, 2012).
acute myeloid leukemia (8 papers, 2014 to 2025). Acute myeloid leukemia (AML) is a group of neoplasms arising from precursor cells committed to the myeloid cell-line differentiation. "NR2F1-AS1 also exerts oncogenic effects by sponging miR-483-3p in acute myeloid leukemia (AML), enhancing IGF1 expression and fostering azacitidine resistance; in osteosarcoma, NR2F1-AS1 targets miR-483-3p to upregulate FOXA1, driving malignant progression." (PMID 41463366, 2025). "These CRC mapping methods, along with pharmacological and genomic studies, have identified critical roles for MYOD, IRF8, FOXA1, and SOX11 TFs in rhabdomyosarcoma, acute myeloid leukaemia (AML), prostate cancer, and neuroblastoma, respectively." (PMID 39536500, 2024).
cervical cancer (8 papers, 2019 to 2025). A primary or metastatic malignant neoplasm involving the cervix. "For instance, in HPV-positive cervical cancer cells, transcription factor FOXA1 activates the expression of circODC1, which in turn promotes cancer cell growth by competitively binding to miR-607, thereby relieving the inhibition on ODC1." (PMID 38956466, 2024). "Empagliflozin activated the AMPK/FOXA1 pathway and inhibited the expression of Sonic Hedgehog Signaling Molecule in cervical cancer." (PMID 35148777, 2022). "Furthermore, FOXA1 is reported to play an essential role in chemoresistance, with high levels contributing to chemoresistance in lung and cervical cancers." (PMID 40623983, 2025). "In the study of cervical cancer, it was found that empagliflozin could activate AMPK phosphorylation, down-regulate the expression of FOXA1, and thus inhibit the expression of SHH, inhibit the malignant proliferation of cervical cancer cells and induce apoptosis." (PMID 40007997, 2025).
bladder tumors (7 papers, 2012 to 2025). "It will be important to correlate FOXA1 expression with disease specific outcome in future studies, and to determine the functional significance of FOXA1 expression for AR and ER activity, as these receptors have been implicated in the molecular pathogenesis of bladder tumors." (PMID 22590586, 2012). "Similar FOXA1 alterations are also detected in other hormone-driven malignancies, including breast, salivary gland, and bladder tumors." (PMID 40570057, 2025). "In this same study, they identified that FOXA1 regulates immune heterogeneity in bladder tumors with SD, an important finding pertaining to response to immune checkpoint inhibitors." (PMID 39513911, 2024). "For this, we utilized RNA-seq data from bladder tumor organoids, with FOXA1 overexpression (OE) in basal and FOXA1 knockout (KO) in luminal tumor organoids." (PMID 38015476, 2024). "In agreement with our PCa data, FOXA1 OE resulted in a significant decrease while FOXA1 KO manifested in a significant increase of NR3C1 expression in bladder tumor organoids." (PMID 38015476, 2024). "FOXA1 was uniformly expressed in stage Ta bladder tumors, compared to only 67% of stage T1 tumors, 59% of stage T2 cancers, 42% of stage T3 tumors, and 34% stage T4 neoplasms." (PMID 22590586, 2012). "Furthermore, FOXA1 transgenic mouse models developed in this study provide a valuable bioresource for studying the pathobiology of breast, salivary gland, and bladder tumors, which harbor recurrent FOXA1 alterations." (PMID 40570057, 2025).
glioma (7 papers, 2016 to 2021). A benign or malignant brain and spinal cord tumor that arises from glial cells (astrocytes, oligodendrocytes, ependymal cells). "Some genes in this locus have been implicated in glioma; the SLC25A21gene is downregulated in GBM, and increased FOXA1 transcription has been reported to promote glioma proliferation." (PMID 32513296, 2020). "miR-200a was shown to inhibit the survival, proliferation and invasion of glioma cells by target regulating FOXA1." (PMID 31842887, 2019). "For example, FOXA1, the most extensively studied member of the family, was found to be up-regulated in many cancers, such as breast, bladder, prostate, glioma and pancreatic cancers." (PMID 27223064, 2016).
Hepatic steatosis (7 papers, 2012 to 2024). Steatosis is a term used to denote lipid accumulation within hepatocytes. "Given that FoxA1 repressed lipid droplet formation via enhancing Sirt6 expression in hepatocytes, we further examined the involvement of Sirt6 in FoxA1 deficiency-mediated hepatic steatosis in mice." (PMID 39277582, 2024). "As determined by HE staining, liver steatosis was promoted by FoxA1 knockout, which was abrogated when Sirt6 was overexpressed at different stages of NAFLD (4, 8, 12 weeks)." (PMID 39277582, 2024). "An earlier study found that FOXA1 reduced steatosis in primary cultured hepatocytes and HepG2, and the expression of FOXA1 was downregulated in both murine models of hepatic steatosis and in human steatotic liver tissue." (PMID 37367037, 2023). "Thus, HFD-induced deSUMOylation of FoxA1 led to hepatic steatosis via inactivation of Sirt6/Pparα pathway." (PMID 39277582, 2024). "Liver FoxA1 knockout mice developed severe liver steatosis, which could be ameliorated by sirtuin 6 (Sirt6) overexpression." (PMID 39277582, 2024). "Furthermore, induction of FOXA1 is an adaptive response to hepatic steatosis and was shown to reduce lipid accumulation in human hepatocytes as is the induction of FGF21 with its great therapeutic potential in the treatment of NAFLD." (PMID 30547786, 2018). "Conversely, induction of FOXA1 highlights adaptive responses to hepatic steatosis." (PMID 30547786, 2018). "Therefore, N800 treatment may induce hepatic steatosis by impairing both Pparα-mediated mitochondrial β-oxidation and Foxa1/Srebp1c-mediated lipid metabolism gene expressions." (PMID 39061900, 2024). "The negative effect of Foxa1 on DGAT2 is of particular relevance as knocking down DGAT2 protects against fat-induced hepatic steatosis and insulin resistance." (PMID 22238690, 2012).
squamous cell carcinoma (7 papers, 2012 to 2023). A carcinoma arising from squamous epithelial cells. "Using sequential in vivo recombination, we find that FoxA1/2 loss in established KRAS-driven neoplasia originating from SPC-positive alveolar cells induces keratinizing squamous cell carcinomas." (PMID 30475207, 2018). "Also, we found that bladder urothelium that has undergone keratinizing squamous metaplasia, a precursor to the development of squamous cell carcinoma (SCC) exhibited loss of FOXA1 expression." (PMID 22590586, 2012).